MYC (MYC proto-oncogene, bHLH transcription factor)
Diseases named in the same sentence as MYC in open-access papers (continued):
Sharing a sentence is not in itself a finding about the gene and the disease.
polycythemia vera (1 paper, 2025). "HHT, a recognized protein synthesis inhibitor, playing a significant role in the treatment of hematological diseases such as AML, CML, MDS, and polycythemia vera by regulating mechanisms including KIT, MYC, MCL-1 and Cyclin-D1." (PMID 40591114, 2025).
prediabetes (1 paper, 2022). "We found out that the TCONS_00334653 and PVT1, whose target mRNA are MYC and HIST1H2BM, were downregulating in the prediabetes with HTG." (PMID 35501901, 2022). "However, our study found out PVT1 was downregulating in the prediabetes with HTG, it might be consistent with that overexpressed MYC is vulnerability to the inhibition of lipogenesis." (PMID 35501901, 2022).
relapsing-remitting multiple sclerosis (1 paper, 2018). The most common clinical variant of multiple sclerosis, characterized by recurrent acute exacerbations of neurologic dysfunction followed by partial or complete recovery. "Another group established an hiPSC cell line from fibroblasts isolated from a patient with relapsing-remitting multiple sclerosis (MS) by retroviral transduction using OCT4, SOX2, KLF4 and c-MYC factors (MSiPS)." (PMID 29439516, 2018).
retinal degeneration (1 paper, 2024). Degeneration of the retina. "As a transcription factor, MYC regulates the cell cycle, metabolism, and apoptosis, disrupting retinal structure and function and indirectly affecting photoreceptor response and neural signal transmission, further promoting retinal degeneration." (PMID 39634176, 2024). "Therefore, SLC7A11 and MYC may directly or indirectly promote retinal degeneration by affecting metabolism, antioxidant defense, cell proliferation, and apoptosis." (PMID 39634176, 2024).
sarcoidosis (1 paper, 2022). Sarcoidosis is a multisystemic disorder of unknown cause characterized by the formation of immune granulomas in involved organs. "In a prior gene co-expression analyses of peripheral blood and cutaneous lesions we noted that transcription factors, such as ETS1, IKZF3, LEF1, MYC, RORA, and SPI1 (PU.1), may be central players in aberrant processes associated with sarcoidosis." (PMID 36311769, 2022).
skin ulceration (1 paper, 2019). "Even if it was observed a positive association of c-MYC RNA levels with skin ulceration (p<0.0001, n = 26), a higher number of animals is required for further validation." (PMID 31461477, 2019). "In parallel, the presence of skin ulceration in cats was found to be associated with c-MYC’s expression, and it was already reported that c-MYC plays a role in the inhibition of epithelialization and wound healing." (PMID 31461477, 2019).
spinal cord ependymoma (1 paper, 2024). An ependymoma that arises from the spinal cord. "Similarly, MYC-amplified spinal cord ependymoma has consistently been shown to have inactivating mutations and loss of heterozygosity of the NF2 gene, which correlates with unfavorable outcomes." (PMID 38254893, 2024).
splenic marginal zone lymphoma (1 paper, 2026). Splenic marginal zone lymphoma is a rare, indolent B-cell non-Hodgkin lymphoma characterized by abnormal clonal proliferation of mature B-lymphocytes with involvement in the spleen, bone marrow and, frequently, the blood. "MYD88 and MYC abnormalities are rarely reported in splenic marginal zone lymphoma (SMZL), and their role in immune dysregulation and transformation remains unclear." (PMID 41756269, 2026).
subarachnoid haemorrhage (1 paper, 2018). "The MYC gene was found having the highest number of strong-related DE miRNAs associated to its regulation, suggesting an important target involved in a complex of subarachnoid haemorrhage." (PMID 29884860, 2018).
Ta (1 paper, 2024). "Our analysis identified two subgroups in Ta tumors: one with FGFR3 alterations linked to LG tumors and favorable outcomes, and another with alterations in ERBB2, PIK3CA, and ERBB3 mutations, and FGFR1, CCND1, and MYC amplifications, associated mostly with HG tumors and poorer prognosis." (PMID 39410541, 2024).
Theileria infection (1 paper, 2025). "Theileria infection normally triggers cytokine secretion such a GM-CSF19, activating TFs (STAT3, PI3-K, AP-1, and E2F) that drive c-MYC production." (PMID 40368139, 2025).
Thrombocytosis (1 paper, 2021). Increased numbers of platelets in the peripheral blood. "The MYC−/− in mice showed not only a diminished lymphocyte production but also demonstrated dysregulated myeloid proliferation, including thrombocytosis, monocyte and neutrophil reduction, and severe anemia." (PMID 34372899, 2021). "Unlike other cells, megakaryocytes were increased in the MYC−/− model, and despite their small size, they could produce high number of platelets, causing thrombocytosis." (PMID 34372899, 2021).
thrombotic disorders (1 paper, 2025). "A disease–gene–drug network was also constructed and visualized using Cytoscape, with MYC positioned as a central hub connecting thrombotic diseases to candidate therapeutic agents." (PMID 41210882, 2025). "The CTD identified MYC and NTAN1 as central players in thrombotic disorders, with MYC linked to 62 diseases and NTAN1 associated with 19 diseases." (PMID 41210882, 2025).
tubular adenoma (1 paper, 2025). A usually polypoid neoplasm arising from the glandular epithelium. "MYC amplification was also prevalent, with an overall occurrence rate of 50.65%, accounting for 71.79% in tubular adenoma patients and reaching 75% in villous adenoma patients." (PMID 40919165, 2025).
ulcerative colitis (1 paper, 2023). An inflammatory bowel disease involving the mucosal surface of the large intestine and rectum. "It was also found that deletion of the rs6651252 enhancer in the HCT116 cell line regulates the expression of the c-MYC proto-oncogene (MYC), associated with Crohn’s disease and ulcerative colitis." (PMID 36969193, 2023).
uterine carcinosarcoma (1 paper, 2021). A usually aggressive malignant neoplasm arising from the uterine corpus and less often the cervix. "The focal amplifications of MYC occur most frequently in ovarian serous cystadenocarcinoma (64.8%), followed by esophageal carcinoma (45.3%), lung squamous cell carcinoma (37.2%), uterine carcinosarcoma, and bladder urothelial carcinoma." (PMID 34503295, 2021).
uterine tumors (1 paper, 2024).
varicocele (1 paper, 2023). A condition characterized by the dilated tortuous veins of the spermatic cord with a marked left-sided predominance. "MYC was also found relevant for transcription regulation of differentially expressed seminal proteins between fertile men and bilateral varicocele patients, known to have fertility issues." (PMID 37892144, 2023).
venous thromboembolism (1 paper, 2025). Occlusion of the lumen of a vein by a thrombus that has migrated from a distal site via the blood stream. "In our study, miR-195 was associated with MYC, and we hypothesize that miR-195 regulates MYC expression, which may be relevant to the treatment of venous thromboembolism." (PMID 41210882, 2025). "In our study, miR-195 is associated with MYC, and we can infer that miR-195 regulates MYC expression, which may be related to the treatment of venous thromboembolism." (PMID 41210882, 2025). "In our study, miR-195 is associated with MYC, suggesting that miR-195 regulates MYC expression and may be related to the treatment of venous thromboembolism." (PMID 41210882, 2025).
visceral leishmaniasis (1 paper, 2021). A severe form of leishmaniasis characterized by irregular bouts of fever, substantial weight loss, swelling of the spleen and liver, and anemia (which may be serious). "Here, we identify genes such as JUN or MYC, which have been reported as overexpressed in visceral leishmaniasis patients." (PMID 34668739, 2021).
ZIKV infection (1 paper, 2018). "On the other hand, ZIKV infection was found to inhibit the expression of MYC, MYCN and NKX2.3 transcription factors, which play roles in cell cycle, proliferation and cellular development." (PMID 30046058, 2018).
tumor (6,898 papers, 1991 to 2026). "Using clinical features and circulating tumor DNA markers (MYC mutations, MYC-immunoglobulin translocations and Epstein-Barr virus fragmentomics), we trained six penalized logistic regression models with tenfold crossvalidation (n = 212)." (PMID 41857199, 2026). "Specific metabolites were identified as preferentially localised in the tumour core, such as pantothenic acid (vitamin B5, m/z 218.10298), which is associated with high MYC expression in human mammary tumours." (PMID 41501078, 2026). "Meanwhile, the analysis of NGS detected two tumor-specific mutated genes: MYC (gene amplification, CN: 59.5) and FLT1 (missense mutation, c.1061G>A (p.R354Q), abundance: 2.1%)." (PMID 42094195, 2026). "Molecular profiling identified NRAS Q61R and TERT promoter mutations, equivocal MYC amplification, and an elevated tumor mutational burden." (PMID 42158418, 2026). "HPV18 status was conserved across the primary tumor, organoids, and xenografts, with an integration site at chr8 (8q24.21) associated with increased MYC expression." (PMID 41828610, 2026). "In human HCC, 81% of CTNNB1-mutated tumours exhibit MYC copy number gain along with significantly increased MYC gene expression." (PMID 41261129, 2026). "High tumor cell proliferation was associated with better survival, MMR deficiency, downregulation of EMT, and upregulation of MYC signaling, alongside an antitumorigenic tumor microenvironment." (PMID 41201451, 2026). "In ROS1-Mut tumors, genes associated with the MYC signaling pathway were significantly upregulated, mediating tumor proliferation, metabolic adaptation, and immune evasion." (PMID 40873541, 2025). "Certain examples of PANTs from oncogenes (e.g. c-MYC) and tumour suppressors (e.g. PTEN) have been previously linked to cancer." (PMID 40276932, 2025). "In parallel, loss of let-7 unleashes HMGA2 and RAS/MYC signaling, a traditional tumor-suppressive axis described across epithelial tumors and reported in gynecologic contexts." (PMID 41226475, 2025). "The spatial locations of tumour cells were determined by the expression of MYC, MYCN and PRDM6, along with other genes associated with proliferation (for example, MKI67)." (PMID 40335697, 2025). "We elucidated the mechanisms by which squamocin induces ER stress, leading to ER‐associated degradation (ERAD) of EZH2 and MYC proteins, ultimately resulting in tumor growth arrest." (PMID 39823459, 2025). "Tumor positivity to c-MYC and ALDH1A1 was associated with longer disease-specific survival, suggesting their potential role in ITAC prediction." (PMID 41463190, 2025). "Hallmark MYC targets V1 and Hallmark MYC targets V2 can enhance cell proliferation and suppress apoptosis by modulating the transcription factor MYC, which is frequently overexpressed in tumor cells." (PMID 41375045, 2025). "Four CAF subpopulations (CAF-0, CAF-1, CAF-2, CAF-3) were identified, revealing differences in key tumor-associated signaling pathways (e.g., MYC, WNT, TGF-β)." (PMID 40589759, 2025). "In terms of signaling pathways, cuproptosis was associated with multiple key tumor molecules, such as E2F and MYC target genes, MTORC1, EGFR, and SMAD signaling molecules." (PMID 41142609, 2025). "On the other hand, it also displayed alterations in the expression of key genes, including SOX9, E2F family, KRAS, BCL2L1, and MYC, indicative of a predisposition for BC tumor initiation, stemness, and progression." (PMID 40801146, 2025). "BRD4 is a pivotal transcriptional regulator of super-enhancer-associated genes linked to tumor progression, such as c-MYC, acting as a scaffold for the recruitment of GRCs that modify chromatin accessibility for TFs." (PMID 40523422, 2025). "We found that the pathways associated with tumor malignancy, such as G2M_CHECKPOINT, E2F_TARGETS, and MYC_TARGETS_V2, were upregulated in Cluster B by GSVA pathway analysis, potentially resulting in poorer prognosis." (PMID 41035672, 2025).
tumor (continued). "Enrichment of IntClust1, 2, and 9 subtypes linked to late recurrence, MYC amplification, and enhanced genomic instability further supports the notion that metastatic ER-positive breast cancer exhibits more aggressive tumor behavior compared to primary disease." (PMID 40858590, 2025). "Dysregulation of the miR-34b/MYC axis has been implicated in tumorigenesis, tumor progression, and therapeutic resistance." (PMID 39129166, 2025). "PVT1 gene fusion is linked to chromothripsis and MYC amplification on chromosome 8q24, further contributing to tumor progression." (PMID 40365336, 2025). "Similar to MYCN-amplified tumours, the common and likely initiating events in the founder clone (C0) were large-scale chromosome 10 loss and/or chromosome 17q gain, with subclonal MYC amplification occurring later during tumour evolution." (PMID 40335697, 2025). "The positive association with E2F and MYC targets further implies that TKT supports tumor proliferation and progression by regulating TFs involved in cell cycle progression and metabolic control." (PMID 40230848, 2025). "The EIF1AX-A113 splice variant, in combination with RAS, stabilizes c-MYC, further accelerating tumor progression." (PMID 40363930, 2025). "The MYC/MAX/MAD network is a key signaling pathway implicated in tumor proliferation, cell adhesion, and angiogenesis." (PMID 40140670, 2025). "Regarding prognosis, E2F1 expression was associated with age, gender, smoking, stage, and tumor size, whereas MYC correlated with smoking, tumor size, and metastasis, and SOX2 was only associated with lymph node metastasis." (PMID 40886002, 2025). "Due to its high frequency of alterations in breast malignancy, its causative role in tumorigenesis/tumor progression and its role in conferring resistance to diverse therapies, MYC is a highly attractive target for new anti-cancer therapies for this disease." (PMID 39875774, 2025). "It promotes tumor progression by regulating critical processes such as proliferation, apoptosis, and cellular differentiation, and is closely linked to MYC, a major oncogene." (PMID 40940795, 2025). "This study demonstrates that 1q21 gain/amplification in MM is associated with an immunosuppressive tumor microenvironment characterized by Treg/Th17 imbalance and MYC overexpression during remission." (PMID 40510369, 2025). "Both CREBBP and p300 have HAT activity; hence, p300 inhibitors can induce synthetic lethality for CREBBP-deficient tumor cells by inhibiting compensatory p300 activation in lung and hematopoietic cancer cells through the regulation of MYC promoter activity." (PMID 40599851, 2025). "MYC deregulation is a hallmark of aggressive cancers and drives tumor growth and therapy resistance across multiple cancer types." (PMID 40668928, 2025). "MYC overexpression canceled Notch activation-induced proliferation arrest of TECs in vitro, and a MYC inhibitor normalized tumor vessels in RBPj deficient mice, suggesting that MYC is the authentic Notch target in normalizing tumor vessels." (PMID 40303332, 2025). "In LUAD, let-7 targets KRAS and MYC, and its downregulation is associated with poor prognosis and increased tumor growth." (PMID 40332376, 2025). "Several hematological malignancies are driven by or associated with MYC dysregulation (Delgado and León, 2010), including neoplasms of B-cells, T-cells, plasma cells, and myeloid lineages (Delgado and León, 2010)." (PMID 41346415, 2025). "In particular, MYC, a well‐known oncogene associated with tumor initiation and progression in cancer, is upregulated in the cancer attractor." (PMID 39840939, 2025).
tumor (continued). "In pediatric gliomas, eccDNA carrying oncogenes such as EGFR and MYC is linked to tumor progression, resistance to radiation and chemotherapy, and enhanced tumor plasticity 24,47." (PMID 40521196, 2025). "The activation of UPR is likely to be a by-product of the MYC-induced hypermetabolic state in the Smarcb1-deficient tumour cells." (PMID 40794298, 2025). "Candidate drivers include ILF2 mutations, amplifications of genes acting downstream of RAS/RAF, such as MYC, or loss of tumour suppressors." (PMID 40849356, 2025). "Given that MYC is aberrantly expressed in nearly 70% of human tumors and is associated with tumor progression, it has long been an attractive therapeutic target." (PMID 40126351, 2025). "Tumor hypoxia detected by MRI was associated with an aggressive MYC-driven gene expression program, suggesting a biologically active tumor with high progression risk." (PMID 41374949, 2025). "In both colony formation assays and xenograft models, the impaired tumor growth caused by USP13 knockout was effectively rescued by MYC-p38α overexpression." (PMID 41307804, 2025). "Elevated levels of MYC are frequently linked to increased tumor aggressiveness and worse clinical outcomes, particularly in two of the four subtypes: ERMS, which shows lower levels of MYC, and ARMS, the subtype characterized by the highest MYC levels." (PMID 40076599, 2025). "Analyses of paired tumours and normal tissues identified increased expression and altered PTMs of proteins linked to cell cycle progression, glycolysis and MYC targets in LUAD samples." (PMID 40849356, 2025). "MYC gene is amplified in several human cancers and is often associated with aggressive tumor growth, increased metastases, and chemoresistance." (PMID 39706891, 2025). "Overall, MYC represents a crucial biomarker for tumor invasion, since it interacts with various genes implicated in cell invasion." (PMID 37450923, 2024). "In previous studies, MYC amplification was found to be associated with larger, more aggressive tumours in patients who are often younger." (PMID 38536546, 2024). "Accordingly, 1,25(OH)2D3 reduced the expression of β-catenin target genes associated with tumour progression such as MYC (Myelocytomatosis) and CCND1 (encoding Cyclin D1)." (PMID 39494323, 2024). "In these tumours, several single nucleotide polymorphisms (SNP) lead to overexpression of MYC and these are associated with the highest odds ratios reported in any cancer type." (PMID 38877600, 2024). "The amplification or overexpression of MYC in various tumors is associated with tumor invasiveness, metastasis, and prognosis." (PMID 38638876, 2024). "HectH9 mediates MYC-mediated entry into the cell cycle; in a human HectH9-deficient tumor cell model, cells are paused at G1 phase." (PMID 37450923, 2024). "Several agents have been reported that can directly or indirectly interfere with MYC expression and exhibit anticancer activity, causing tumor regression in preclinical stage studies." (PMID 37450923, 2024).